POLM (DNA polymerase mu)
Description:
Catalyzes template-directed nucleotide addition during gap filling at DNA double-strand breaks. Functions as a gap-filling polymerase involved in repair of DNA double-strand breaks by non-homologous end joining (NHEJ). Displays reduced sugar discrimination, incorporating deoxyribonucleotides and ribonucleotides with similar efficiency on DNA primer strands, and is able to polymerize nucleotides on RNA-terminated primer strands in vitro. Participates in immunoglobulin (Ig) light chain gene rearrangement in V(D)J recombination (By similarity).
Synonyms: Pol Mu; Tdt-N
Tractability: Small molecule: a structure with a bound ligand is known. PROTAC: ubiquitination databases record sites on it; a small molecule that binds it is known.
Target class: Enzyme; Transferase
Gene: Protein-coding gene on chromosome 7 (44,070,915 to 44,082,530, reverse strand). Ensembl gene ENSG00000122678.
Subcellular location: Nucleus
Subcellular location (Human Protein Atlas): Nucleoplasm
Pathways (Reactome):
DNA Repair: Nonhomologous End-Joining (NHEJ)
Gene Ontology:
Molecular function: DNA-directed DNA polymerase activity; magnesium ion binding; protein binding; DNA binding; DNA polymerase activity; nucleotidyltransferase activity
Biological process: double-strand break repair via nonhomologous end joining; DNA biosynthetic process; DNA repair
Cellular component: nucleoplasm; nucleus
Genetic constraint (gnomAD): Loss-of-function variants: 54 observed, 57.55 expected, observed/expected ratio (o/e) 0.94, 90% interval 0.75 to 1.18. The upper end of that interval is the gene's LOEUF score, 1.18, which puts it in group 5 of 6, group 1 being the genes least tolerant of losing a copy. Missense variants: 660 observed, 623.61 expected, observed/expected ratio (o/e) 1.06, 90% interval 0.99 to 1.13. Synonymous variants: 273 observed, 251.61 expected, observed/expected ratio (o/e) 1.09, 90% interval 0.98 to 1.2.
Homologues: Orthologues: chimpanzee POLM (99% identical), macaque POLM (95% identical), rabbit POLM (80% identical), pig POLM (79% identical), mouse Polm (76% identical), rat Polm (75% identical), guinea pig POLM (71% identical), dog POLM (68% identical), zebrafish polm (49% identical), tropical clawed frog polm (45% identical). Paralogues in human: DNTT (41% identical), POLL (27% identical), POLB (16% identical).
Diseases named in the same sentence as POLM in open-access papers:
POLM is named in the same sentence as 10 diseases in open-access papers, as found by Europe PMC text mining. Sharing a sentence is not in itself a finding about the gene and the disease. The quoted sentences say what the papers report.
anemia (1 paper, 2021). A reduction in the number of red blood cells, the amount of hemoglobin, and/or the volume of packed red blood cells. "Also in the signature were genes encoding the DNA glycosylase NEIL3, Fanconi Anemia factors (FANCD2, UBE2T), the ubiquitin protein ligase UBE3B, and two specialized DNA polymerases, POLM and POLQ, involved in the non-homologous end-joining (NHEJ) pathways of DSB repair." (PMID 34067180, 2021).
Hernia (1 paper, 2023). "Yet the presence of a group of mutated genes linked to myopathies (ITGA7, NRAP, POLM, SCN5A, XIRP2) and muscular dystrophy (ITGA7) raises a question about the involvement of these muscular pathologies in hernia genesis and unsuccessful hernia repairs associated with the current case." (PMID 38021525, 2023).
viral infection (1 paper, 2025). "In this study, we offer evidence for a novel anti-viral infection mechanism mediated by POLM." (PMID 39927776, 2025).
cancer (7 papers, 2017 to 2025). A tumor composed of atypical neoplastic, often pleomorphic cells that invade other tissues. "Although variants in POLM have not been directly associated with cancer risk, it is a putative predisposition gene since variants in other DNA polymerase genes (POLD1 and POLE) have already been related to CRC risk." (PMID 39408606, 2024). "Another notably amplified gene was POLM (13.6%, 21/154), which has not been studied in cancers yet." (PMID 33178606, 2020).
infection (3 papers, 2009 to 2025). The state of being infected such as from the introduction of a foreign agent such as serum, vaccine, antigenic substance or organism. "We found that the newly discovered host anti-viral factor POLM could be regulated by FOXA1 in the infection process with PEDV." (PMID 39927776, 2025). "Furthermore, POLM was observed to be downregulated during infection, possibly affecting the processing of DSBs ends and the implementation of end-joining." (PMID 33339161, 2020). "Our article describes how DNA polymerase mu (Polμ), a recently identified component of the NHEJ machinery, is required for hematopoiesis—the process that generates and maintains the correct balance of the millions of blood cells needed to sustain life and defend against infection." (PMID 19229323, 2009).
tumor (2 papers, 2017 to 2023). "Among DNA repair genes, we detected evidence of positive selection in the tumor suppressor-encoding PALB2 and in four DNA polymerase-encoding genes (POLA1, POLD1, POLK, and POLM)." (PMID 37728212, 2023).
POLM also shares sentences with these, for which no sentence is quoted: breast carcinoma (1 paper); lung carcinoma (1); muscular dystrophy (1); myopathies (1).